FGF23 (fibroblast growth factor 23)
Diseases named in the same sentence as FGF23 in open-access papers (continued):
Sharing a sentence is not in itself a finding about the gene and the disease.
kidney disease (continued). "As renal disease progressed, despite the increasing FGF23 levels, fractional phosphorus excretion decreased possibly due to a lower renal Klotho expression and a reduction in functioning nephrons, with the net result of increased serum phosphate levels." (PMID 23967103, 2013). "Using stored samples, plasma FGF23 was determined in 604 patients with moderate to severe kidney disease that participated in the MASTERPLAN study (ISRCTN73187232)." (PMID 22530966, 2012). "Here, we investigated the consequences of FGF23 excess in kidney disease." (PMID 41744000, 2026). "The present data provide evidence that excess FGF23 directly drives inflammation in kidney disease and may serve as a therapeutic target." (PMID 41744000, 2026). "However, iPTH, phosphate, and calcium correlated only with the renal disease progression, while FGF-23 and klotho were affected by CKD and CVD." (PMID 40002748, 2025). "In patients with CKD, higher levels of FGF23 are associated with progression of kidney disease and mortality independent of other risk factors." (PMID 38124483, 2024). "FGF-23 was proven to be the first hormone to respond in the “updated trade-off hypothesis” and could serve as an earlier marker for kidney disease." (PMID 38785509, 2024). "FGF23 can be considered a biomarker of musculoskeletal and kidney diseases in SLE patients." (PMID 37627287, 2023). "None of the three assays were able to clearly differentiate between study groups I and II, or II and III, which suggests that FGF-23 may be suboptimal for the early detection of CKD or the monitoring of early-stage kidney disease." (PMID 37889764, 2023). "It is also suggested that FGF-23 may be suboptimal for the early detection of CKD or the monitoring of early-stage kidney disease." (PMID 37893926, 2023). "FGF‐23 plays a crucial regulatory role and is acknowledged as early marker of renal disease." (PMID 38053473, 2023). "While FGF-23 plasma concentration always increases in the early stages of kidney disease, patients with end-stage kidney disease who have started hemodialysis demonstrated a much more pronounded increase in plasma FGF-23 than expected for the degree of kidney dysfunction." (PMID 36688811, 2023). "FGF-23 might be, therefore, an attractive potential tool for therapeutic decision regarding phosphorus control in early kidney disease in cats." (PMID 37889764, 2023). "The osteocytes-derived fibroblast growth factor 23 (FGF23), principally implicated in phosphate and vitamin D regulation, is considered a promising and early CKD biomarker, which starts to increase from the beginning of renal diseases." (PMID 36569120, 2022). "As such, the disturbances in the mineral homeostasis start early in kidney disease with a reduction of α-Klotho and an increase in fibroblast growth factor 23 (FGF23), this is followed by a downregulation of the active vitamin D metabolite 1,25 dihydroxy vitamin D3 (1,25 vitamin D)." (PMID 34940607, 2021). "Therefore, serum LCN2 emerges as a major kidney-bone crosstalk molecule that links the inflammation of kidney disease to FGF23 secretion from the bone and the development of cardiac disease during CKD." (PMID 34334787, 2021). "Given that kidney diseases are often linked to CVD, recent studies have started to explore the role of kidney-function-related biomarkers, such as fibroblast growth factor 23 (FGF23) in CVD." (PMID 34367258, 2021). "On the other hand, some studies have demonstrated that, in the presence of significant renal disease, high levels of FGF23 may be necessary to control mineral metabolism and that an excessive reduction in FGF23 could be detrimental." (PMID 33374582, 2020). "We excluded patients with advanced kidney disease and those on treatment with vitamin D, calcium or phosphate supplements or binders as this may influence Klotho and FGF23 levels and could confound interpretation of the results." (PMID 33225726, 2020).
kidney disease (continued). "FGF23 has also been shown to independently predict progression of renal disease, however, whether FGF23 and FGFR4 also contribute to CKD remains unknown." (PMID 31575945, 2019). "Thus far, in the context of kidney disease, renal expression of FGF23 has only been definitively identified in the obese Zucker rat29 and rodent models of polycystic kidney disease." (PMID 28611350, 2017). "Advanced glycation end products (AGEs) may induce cardiac remodeling in kidney disease by promoting fibroblast growth factor 23 (FGF-23) expression." (PMID 29147074, 2017). "Furthermore, our findings of the independent associations of higher FGF23 levels at baseline with more rapid carotid IMT progression and with progressive albuminuria suggest a role for FGF23 in cardiovascular and kidney disease in HIV-positive populations." (PMID 27176000, 2016). "In conclusion, our results favor the hypothesis that renal Klotho synthesis diminishes early in renal disease and that s-Klotho proportionally lessens; bone detects these changes somehow and increases FGF23 production." (PMID 25873958, 2015). "However, previous studies that evaluated vitamin D and FGF-23 have shown the prognostic value of calcium in renal disease." (PMID 25412875, 2014). "The relation between FGF-23 and cognitive function is largely unknown, both in patients with kidney disease or in any population." (PMID 25208315, 2014). "So, a plausible explanation for our results is that we evaluated FGF-23 levels in a very early development of renal disease, without loss of renal function." (PMID 25222475, 2014). "Besides mineral metabolism, Klotho FGFR1c-FGF23 axis is considered to be a predictor of progression of kidney disease and to be related to morbidity and mortality." (PMID 25295189, 2014). "FGF23 bone expression was approximately 30 times higher than renal expression in normal conditions, but no data are available that compared tissues from patients with renal disease." (PMID 23967103, 2013). "We identified several genes regulated by FGF23 that may link this hormone to processes responsible for progression of kidney disease as well as pathways responsible for adverse cardiovascular outcomes." (PMID 22970174, 2012). "The central role of these pathways, together with IL1-beta, another pro-inflammatory cytokine, demonstrate that the inflammatory state that correlates with kidney disease may be modified by FGF23." (PMID 22970174, 2012). "Hence, increased renal production of oncostatin M may also contribute to the enhanced FGF23 production characteristic of kidney disease." (PMID 37225713, 2023). "However, there are also reports indicating an association between FGF-23 and cardiovascular (CV) mortality even in the absence of kidney disease." (PMID 35159318, 2022). "Therefore, the estimation of serum Klotho protein due to calcium and sodium dysregulation in renal diseases and the novel link between FGF23 and the metabolism of these ions may have major pathophysiological implications in CKD." (PMID 35812534, 2022). "However, high FGF-23 levels correlate with morbidity and mortality in patients with renal disease." (PMID 36246903, 2022). "Future studies should explore the mechanisms underpinning such relations, which may help explain the discrepant results concerning the role of FGF23 in CVD, T2DM, and kidney diseases across different studies, and further elucidate the role of FGF23 in these diseases." (PMID 34367258, 2021). "Lane showed that an increased level of serum FGF-23 enhanced the risk of fractures in patients with a glomerular filtration rate less than 60 mL min−1 (1.73 m2)−1, which suggested that the level of FGF-23 was correlated with a change in BMD in renal disease patients." (PMID 29665846, 2018). "However the mechanisms’ underlying the associations between FGF-23 and GDF-15 on one side and mortality and renal disease on the other remains unclear." (PMID 29698460, 2018).
kidney disease (continued). "Fibroblast growth factor 23 (FGF23), which was initially characterized in a study of rare inherited disorders associated with phosphate metabolism, regulates phosphate homeostasis and explains the decreases in 1,25-OH vitamin D in patients with early kidney disease." (PMID 26241225, 2015). "A receptor for fibroblast growth factor-23 (FGF-23), α-Klotho is a monotransmembrane anti-aging protein whose role in kidney disease has been extensively studied." (PMID 37865763, 2023). "In aggregate, our results demonstrate that DMP1 decreases FGF23 levels in CKD, independently of mode of administration, age, mouse strain, kidney disease progression, phosphate, or PTH levels." (PMID 31044094, 2019). "In the early stage of CKD, fibroblast growth factor 23 (FGF23) level increases before parathyroid hormone (PTH) and phosphate levels increase, and steadily increases with the progression of kidney disease." (PMID 23013306, 2012). "In CKD, fibroblast growth factor 23 (FGF23) level increases early before PTH and phosphate levels increase, and steadily increases with the progression of kidney disease." (PMID 23013306, 2012). "Participants in the present study did not suffer from renal disorders, potentially accounting for the lack of correlation between CSF FGF23 levels and cognition." (PMID 40792551, 2025). "In CKD, both FGF23 and parathyroid levels increase, so they act as markers of CKD, but FGF23 levels rise before other markers like parathyroid hormone and phosphorus in people with early kidney disease." (PMID 40559238, 2025). "FGF23 levels increased with CKD progression, and MBD was more prevalent in advanced kidney disease." (PMID 39433982, 2024). "FGF23 levels increased as CKD progressed, and MBD was more prevalent in advanced kidney disease." (PMID 39433982, 2024). "Our findings that iFGF23 is an independent predictor of outcome in patients with HF is in line with previous evidence reporting FGF23 as a correlate of HF-related outcome, in patient with or without kidney disease." (PMID 37658340, 2023). "To our knowledge, we report the first randomized placebo-controlled trial to assess the effect of oral iron supplementation on FGF23 concentrations in persons without kidney disease." (PMID 33675347, 2021). "Actually, the relationship between high FGF23 and mortality is not restricted to patients with kidney disease but has also been identified in the general population." (PMID 33374582, 2020). "We established PTH target values of 100–300 pg/ml considering the Kidney Disease: Improving Global Outcomes guidelines in order to demonstrate the effect of FGF23 independent of PTH." (PMID 31651370, 2019). "Herein, we show that lack of the −16kb enhancer of Fgf23 prevented early onset kidney disease‐induced increases in renal, thymic, and skeletal Fgf23 expression in a diet‐induced CKD model." (PMID 29527594, 2018). "In the MMKD study that enrolled only nondiabetic patients with mild-to-moderate kidney disease, both intact and C-terminal FGF23 levels independently predicted renal outcome (same definition as our study)." (PMID 29270765, 2018). "Notably, circulating levels of fibroblast growth factor 23 (FGF23), which plays a key role in the endocrine regulation of phosphate homeostasis, are elevated very early in kidney disease." (PMID 24795646, 2014). "α-klotho acting as a scaffold for FGF23 binding to the FGFR1-3 receptors has actions independent from FGF23 that include cleavage of NaPi-IIa transporters, regulation of transient receptor potential cation channel subfamily V member 5 (TRPV5) calcium channels and modulation of renal disease." (PMID 37660247, 2024). "However, in patients with kidney disease or anuric patients, as in our study, high levels of FGF-23 do not have a phosphaturic action." (PMID 39768249, 2024).
kidney disease (continued). "Both cardiovascular and kidney disease have a broad spectrum of etiologies and clinical presentation, but during progression of each disease, two hallmarks are an activation of the renin–angiotensin–aldosterone system (RAS), and a rise in serum concentrations of fibroblast growth factor 23 (FGF23)." (PMID 35201364, 2022). "The elevated FGF-23 may reflect tubular dysfunction and resistance to endocrine factors in kidney disease, an important pathology not fully captured by measurement of GFR or albuminuria." (PMID 31246994, 2019). "Growing evidence indicates that measurement of FGF-23 may serve as a biomarker that provides evidence for a disordered mineral ion homeostasis in CKD patients and predicts abnormal bone mineralization, kidney disease progression, vascular calcifications, and overall mortality." (PMID 20593414, 2010).
bone disorder (58 papers, 2013 to 2026). "Fibroblast growth factor 23 is a key regulatory factor for phosphate homeostasis and is implicated in a range of hypophosphatemic bone disorders." (PMID 41445552, 2025). "Combined with other still scarce data on intact FGF23 values in healthy children, we provide an useful tool for recognising the early onset of otherwise asymptomatic early stages of bone disorders in children of the population at risk, especially CKD children." (PMID 34258392, 2021). "Further studies are warranted to determine more precisely the mechanism tying these pathophysiological processes together and whether serum biomarkers of CKD-mineral and bone disorder, such as FGF-23, can be used clinically for better CV risk stratification." (PMID 27805564, 2016). "Building on this initial research, the advent of burosumab—a monoclonal antibody targeting FGF23—has changed the landscape of FGF23 mediated bone disorders, particularly XLH." (PMID 41445552, 2025). "Klotho modulates the calcium and mineral homeostasis and the triad composed by α-Klotho, fibroblast growth factor-23, and its receptor is involved in the pathogenesis of mineral and bone disorder in CKD." (PMID 34206780, 2021). "The association between inflammatory cytokines and bone disorders markers, OPN, OPG, and FGF-23, reflects the severity of the vascular changes in CKD and predicts the disease progression." (PMID 27667892, 2016). "The association between inflammatory cytokines and bone disorders markers, IL-6, TNF-α, OPN, OPG, and FGF-23, reflects the severity of vascular changes in CKD and predicts disease progression." (PMID 27667892, 2016). "Understanding the broader implications of FGF23 overexpression on bone and systemic health could lead to improved treatments for skeletal diseases." (PMID 39329699, 2024). "Further, Phd2 is a critical mediator of osteocyte FGF23 production, thus our collective studies may provide new therapeutic targets for skeletal diseases involving disturbed oxygen/iron sensing." (PMID 36650133, 2023). "Therefore, our data support a potential therapeutic advantage of combined DMP1 repletion and FGF23 blockade to effectively correct ARHR-associated mineral and bone disorders." (PMID 37943605, 2023). "Our data suggest that combined DMP1 repletion and FGF23 blockade could effectively correct ARHR-associated mineral and bone disorders." (PMID 37943605, 2023). "The clinical impact of serum FGF23 elevation in mineral and bone disorders (MBD) may be different among various stages of CKD." (PMID 27504998, 2016). "This process is further influenced by the CKD–mineral and bone disorder (CKD–MBD) axis, where imbalances in calcium, phosphate, parathyroid hormone (PTH), and fibroblast growth factor 23 (FGF23) drive both skeletal and vascular pathology." (PMID 41470171, 2025). "FGF-23 is a useful biomarker for the identification and better understanding of CKD–mineral and bone disorder." (PMID 38891718, 2024). "Beyond these rare diseases, an increase in FGF23 concentration is the first detectable change in mineral metabolism in CKD-mineral and bone disorder." (PMID 35736431, 2022). "Seventh, fibroblast growth factor 23 (FGF 23) plays an important role in the mineral and bone disorders of CKD patients." (PMID 28841848, 2017). "In fact, FGF23 and bone-kidney axis act as a biological route which have recently been discovered as the main players in CKD-mineral and bone disorder (CKD-MBD)." (PMID 27471744, 2016). "Further studies in adult patients are needed to evaluate FGF-23 expression in bone together with other factors potentially contributing to the regulation of bone formation and mineralization in CKD-mineral and bone disorders." (PMID 25208316, 2014). "With no history of skeletal disease in his family members and an acquired form of his condition, TIO, which is the most prevalent cause of acquired FGF23-related hypophosphatemic osteomalacia, was initially diagnosed." (PMID 39963340, 2025).
bone disorder (continued). "Alongside comparable plasma levels of bone disorder biomarkers—including serum calcium and phosphate, 25-OH vitamin D, 1,25-OH vitamin D, PTH, and FGF23—the average values of S100A12/ENRAGE, pentosidine, RAGE, and myeloperoxidase at baseline were very similar in the two study arms." (PMID 29362665, 2017). "A panel of proteomic biomarkers, assessed by xMAP array, which includes mediators of inflammation (IL-6, TNF-α) and mineral and bone disorder biomarkers (OPG, OPN, OCN, FGF-23, and Fetuin-A), was found to be more relevant than a single biomarker to detect early CKD stages." (PMID 27667892, 2016). "Out of all analyzed candidate biomarkers, a panel which includes mediators of inflammation (IL-6, TNF-α) and mineral and bone disorder biomarkers (OPG, OPN, OCN, FGF-23, and Fetuin-A) was found to be more relevant than a single biomarker to detect patients in early CKD stages." (PMID 27667892, 2016). "Moreover, in ACKD, mineral–bone disorders may have been subclinical before the acute event, as FGF-23 (Fibroblast Growth Factor-23) typically rises before CaxP abnormalities become evident." (PMID 41295735, 2025). "The type of bone disorder in CKD has not been related to FGF23 expression." (PMID 33233840, 2020).